TNF (tumor necrosis factor)
Diseases named in the same sentence as TNF in open-access papers (continued):
Sharing a sentence is not in itself a finding about the gene and the disease.
fibrosis (continued). "Anti-TNF-α treatments demonstrated the beneficial effects on BLM-induced pulmonary inflammation and fibrosis, both in vivo and in vitro." (PMID 24300094, 2013). "Transient elastography-based classification showed no significant TNF-α differences between mild (36.1 ± 30.2 pg/mL), moderate (43.1 ± 26.9 pg/mL), and severe (45.8 ± 26.4 pg/mL) fibrosis groups (p = 0.17)." (PMID 41590632, 2025). "Higher levels of pro-inflammatory cytokines IFNγ, IL-6, IL-8 and TNFα were found in MASLD with fibrosis patients compared with MASLD without fibrosis." (PMID 38235661, 2024). "We also found elevated levels of IL-6 and TNF-α in the fibrosis groups (F2–F4), but these results were not significant." (PMID 39272729, 2024). "Fibrosis is marked by an increase in the inflammatory response, tissue destruction, and the release of numerous inflammatory cytokines, including TGF-β1, tumor necrosis factor-alpha (TNF-α), monocyte chemoattractant protein (MCP-1), Interleukin-6 (IL-6), and IL-8." (PMID 36835428, 2023). "Thus, g-EAT thyroid samples with fibrosis showed a higher presence of TGF-β and TNF-α than the control samples." (PMID 36834770, 2023). "Recent anti-inflammatory therapies, chiefly anti-TNF (tumor necrosis factor) agents, have not been proven to be effective in preventing intestinal fibrosis." (PMID 35645830, 2022). "BLM administration increase lung concentrations of IL-1β (69.16 ± 2.69 vs. 27.36 ± 1.37, p < 0.005, t-test), IL-6 (104.7 ± 13.45 vs. 17.466, p < 0.02, t-test), and TNF-α (500.09 ± 42.19 vs. 58.84 ± 4.51, p < 0.05, t-test) observed in BLM-induced fibrosis group, compared to controls." (PMID 35326173, 2022). "They release IL-1β, IL-6, tumor necrosis factor α (TNFα), and MCP-1, which may contribute to cardiac fibrosis and diastolic dysfunction." (PMID 34387811, 2022). "Notably, L. minor lung protection markedly decreased in the IL-1β levels (by 38.82 ± 5.41, p < 0.0003, t-test) and TNF-α levels (by 232.87 ± 35.09, p < 0.0062, t-test), compared to BLM-induced fibrosis group, on the course 33 days, respectively." (PMID 35326173, 2022). "In addition, cytokines like tumor necrosis factor (TNF) and interleukin (IL)-1β stored in MC granule (MCG) can also promote cardiac fibrosis through cardiomyocyte apoptosis during degranulation." (PMID 34485413, 2021). "The expression levels of IL-1β, IL-6, IL-17, TNF-α, TGF-β, and α-SMA (as a myofibroblast marker) were all decreased by anakinra treatment, which suggested anti-inflammatory and antifibrotic effects of the IL-1Ra in this BLM-induced fibrosis model." (PMID 30042768, 2018). "Furthermore, IL-17a and the mRNA expression levels of IL-6, TNF-α and TGF-β1 were decreased in the liver tissues of the IDO1–/– fibrosis mice compared with the WT fibrosis mice." (PMID 28465467, 2017). "In contrast, no significant change in interstitial and perivascular fibrosis was observed in Ang II infused TNF-α-/- mice." (PMID 26378790, 2015). "In the present study it was observed that cells of individuals with incipient or moderate to severe fibrosis, even without antigenic stimuli, produced higher levels of TNF-α when compared to those without fibrosis." (PMID 23320145, 2012). "The involvement of TNFα in intestinal fibrosis has not been fully elucidated." (PMID 39428941, 2025). "The attenuating effect of BSE-CD on liver granuloma and fibrosis was accompanied by decreased MCP-1, TNF-α, and VEGF levels expression, which may contribute to the inhibition of macrophage recruitment, and to the reduction of peri-ovular inflammatory responses and vasculogenesis." (PMID 24941000, 2014). "Supporting the role of TNF-α in the development of liver pathology due to schistosomiasis, a study conducted in a schistosomiasis endemic area in Brazil has demonstrated that individuals with moderate to severe periportal fibrosis have higher serum levels of TNF-α than those without fibrosis." (PMID 23320145, 2012).
fibrosis (continued). "Moreover, the levels of TNF-α in nonstimulated cultures were higher in individuals with moderate to severe fibrosis (median levels = 488.7 pg/mL) compared to subjects without periportal fibrosis (median levels = 61.9 pg/mL; P = 0.0182)." (PMID 23320145, 2012). "Melatonin supplementation, however, reduced cardiac fibrosis and significantly decreased the expression of IL-1α and IL-6 in WT and NLRP3−/− mice, with non-significant decline of TNFα." (PMID 34439517, 2021). "In contrast to the IL-6 and VCAM-1 results, CRP, TNFα, MCP-1, MIP-1β, and eotaxin levels did not change with fibrosis severity." (PMID 31291245, 2019). "Similarly, tumor necrosis factor (TNF)-α levels in lung tissue and BAL were not different between CPFE patients and those with fibrosis alone." (PMID 37174678, 2023).
pancreatitis (159 papers, 2007 to 2026). Inflammation of the pancreas. "For instance, the injection of TNFerade, an adenovirus vector expressing TNF-α, led to local inflammatory responses such as pancreatitis and cholangitis, which were strongly associated with the dosage and local drug buildup." (PMID 41463644, 2025). "In pancreatitis-induced lung injury, apigenin was associated with decreased TNF-α, IL-6, and MPO expression, indicating attenuation of both cytokine-mediated and oxidative damage." (PMID 40429525, 2025). "Our analysis also indicated that TNF inhibitors can be negatively associated with pancreatitis, for example, for ETN." (PMID 39712842, 2024). "Our analysis reveals an increasing trend in the pancreatitis risk with TNF inhibitors when stratified by year, with all of the TNF inhibitors studied exhibiting significant association with pancreatitis in the year 2023." (PMID 39712842, 2024). "Our findings flag the necessity for a careful investigation and monitoring of pancreatitis risk in patients undergoing TNF inhibitor therapy, especially in recent years." (PMID 39712842, 2024). "Next, we considered the same disproportionality analysis, but stratified by year, to investigate the trends of the pancreatitis risk with TNF inhibitors over time." (PMID 39712842, 2024). "The importance of pro-inflammatory cytokines in pancreatitis has been highlighted by a recent study in 84 patients with AP who were screened for known polymorphisms in TNFα, interleukin 1 (IL-1), IL-1 receptor antagonist (IL1RN), IL-6, and IL-10." (PMID 30681551, 2019). "Mlkl, which was recently described to interact with Rip3 and to participate in TNFα-induced pancreatitis-associated necroptosis, was also significantly elevated in Atg7Δpan pancreata." (PMID 28703808, 2017). "Results from these two independent studies suggest that the deletion of MK2 most likely ameliorates cerulein-induced pancreatitis in mice by decreasing the production of TNF-α and IL-6, thereby reducing inflammatory injuries caused by these cytokines." (PMID 24705157, 2013). "The frequencies of TNFα polymorphisms were both similar in patients with mild or severe pancreatitis, so were in pancreatitis patients and in controls." (PMID 20396411, 2010). "Moreover, rare cases of pancreatitis associated with TNF-α inhibitors underscore the need for careful evaluation of potential adverse events." (PMID 41530118, 2026). "However, the role of ethnicity in thiopurine-induced pancreatitis remains unexplored, and while anti-TNF therapy has been associated with renal dysfunction, there have been no studies examining the impact of ethnicity in this context." (PMID 41497517, 2025). "Both conditions may share pro-inflammatory cytokines, such as IL-33 and TNF-α, which intensify inflammation and predispose individuals to pancreatitis." (PMID 40417313, 2025). "It is unclear whether the increased TNF-α in the brain of the hyperglycemic mice originates from β cells caused by pancreatitis or from microglial cells due to inflammation in the brain." (PMID 40559659, 2025). "Therefore, we believe that an important direction for future research is to study what makes TNF inhibitors protective against pancreatitis in certain settings and what makes TNF inhibitors risk factors for pancreatitis in others." (PMID 39712842, 2024). "This study has several limitations that could be improved upon in future studies on TNF inhibitor-associated pancreatitis." (PMID 39712842, 2024). "A case–control study (NCT04131478) was conducted primarily to determine the incidence of TNF-α 308 G/A (rs1800629) and −1031T/C (rs1799964) gene polymorphisms in adult Egyptian patients with local/advanced or metastatic pancreatic or NSCL cancer and investigate both as cachexia risk factors." (PMID 34900737, 2021).
pancreatitis (continued). "Specifically, Zn sulfate supplementation in rats with pancreatitis significantly reduced endotoxic accumulation (LPS) and tissue IL-1β and TNFα expression, as well as attenuated pancreatitis-associated gut permeability and bacterial translocation to pancreas, liver, and mesenterial lymph nodes." (PMID 34884881, 2021). "In vitro studies further indicated that isolated PSCs could activate in response to a number of pancreatitis-associated cues, including transforming growth factor Beta (TGFβ), tumor necrosis factor alpha (TNFα), and ethanol." (PMID 33198201, 2020). "TNF-α is known to cause apoptosis in acinar cells in experimental pancreatitis in rodents." (PMID 29127325, 2017). "Furthermore, in a pancreatitis model, polyamines could prevent damage to membrane structure caused by activated oxygen radicals by preventing the production of TNF-α and IL-6 production." (PMID 40141396, 2025). "Furthermore, TNF‐α, IL‐6 and IL‐1β expression has shown a close correlation with the infiltration of activated inflammatory cells into the pancreas and is also associated with the severity of pancreatitis." (PMID 27957800, 2017). "TNF-alpha is a pro-inflammatory cytokine, and its serum concentration has been shown to correlate with the severity of pancreatitis in both animal models and humans." (PMID 40507369, 2025). "In another study involving rats with sodium taurocholate-induced pancreatitis, pentoxifylline (a TNF-alpha inhibitor) and oxypurinol (an inhibitor of xanthine oxidase) were administered to inhibit oxidative stress." (PMID 40507369, 2025). "TNF-α peaked on day 1 in patients with moderate/severe pancreatitis, whereas TNF-α peaked on day 4 in patients with mild pancreatitis." (PMID 40411704, 2025). "In severe cases, pancreatitis can lead to the release of cytokines such as Interleukin-1, Interleukin-6, and Tumor Necrosis Factor-α, which activate neutrophils, monocytes, lymphocytes, and platelets, worsening the inflammatory response." (PMID 40429414, 2025). "This indicates that reports of pancreatitis adverse events are distributed more among these indications of TNF inhibitor therapy." (PMID 39712842, 2024). "TNF-α, IL-1β, and IL-10 levels increased significantly (P<0.05) in pancreatitis compared to the control group." (PMID 38333760, 2024). "In the present study, TNF-α and IL-1β levels were significantly lower than those of the pancreatitis group as a result of pre-application of melatonin." (PMID 38333760, 2024). "Carbon monoxide releasing molecule has been found to inhibit TLR4 signaling in macrophages leading to reduced production of TNFα and proinflammatory cytokines in cerulein-induced pancreatitis." (PMID 38585277, 2024). "Cer-pancreatitis induction resulted in a significant elevation of the inflammation markers TNFα and IL-6, accompanied by the reduction in cell viability in a time-dependent manner, indicating that prolonged (24 h) cer treatment mimic AP state in vitro." (PMID 38927047, 2024). "Cer-pancreatitis significantly elevated TNFα expression levels by 36-fold (transcript) and by 4-fold (protein)." (PMID 38927047, 2024). "Plasma TNF-α level was significantly lower in severe pancreatitis compared to sham-operated controls at both 0.5 and 6 hours after the onset of the condition." (PMID 39139157, 2024). "The role of SOCS3 in the activation of macrophages in pancreatitis is further supported by a study showing that macrophage-specific deletion of SOCS3 developed less severe pancreatitis and produced less TNFα in response to cerulein injections." (PMID 38585277, 2024). "Together, our findings highlight the necessity for careful monitoring of pancreatitis in patients undergoing TNF inhibitor therapy." (PMID 39712842, 2024). "TNF-α and IL-1β levels in the melatonin-treated pancreatitis group were significantly lower than in the pancreatitis group (P<0.05)." (PMID 38333760, 2024).
pancreatitis (continued). "Significantly, experimental studies have indicated the potential advantages of targeting TNF, reducing leukocyte infiltration, and curtailing cytokine release in experimental therapies for pancreatitis." (PMID 39372399, 2024). "A particularly notable example is a combination therapy of TNF inhibitors with azathioprine (AZA), which has been known for its association with drug-induced pancreatitis for decades." (PMID 39712842, 2024). "The levels of inflammatory cytokines, especially proinflammatory cytokines such as IL-6, IL-1β and TNF-α, which are indicators of severity in pancreatitis, are also important." (PMID 38698325, 2024). "Pathogenic mediators, such as reactive oxygen species, proinflammatory markers, and tumor necrosis factor (TNF)-α from steatohepatitis liver, can promote kidney injury, pancreatitis, and splenomegaly." (PMID 38399435, 2024). "In untreated animals with pancreatitis, there was a significant surge in TNF-α activity in the bloodstream during the first three hours after the onset of the disease." (PMID 39139157, 2024). "Our study conducted in human samples also identified the role of IL-6 and TNF-α in developing pancreatitis." (PMID 38533139, 2024). "Among the TNF inhibitors, we found that IFX had the highest risk for pancreatitis across all measures of disproportionality, with an ROR of 2.13 (95% CI, 2.02, 2.24)." (PMID 39712842, 2024). "Cer-pancreatitis resulted in a significant up-regulation of inflammation markers such as TNFα and IL-6." (PMID 38927047, 2024). "By targeting RIPK1-driven necroptotic pathway, Vemurafenib alleviated TNFα-induced systemic inflammation and caerulein-induced pancreatitis in murine disease models." (PMID 37620300, 2023). "Previous studies have documented the anti-inflammatory activity of lawsone in different in vivo inflammatory models, like pancreatitis and carrageenan-induced inflammatory edema, and are suggestive of its effect through the modulation of TNFα and NF-кB." (PMID 37763713, 2023). "The administration of gs-4997 to mice with pancreatitis largely reduced the upregulation of IL-6, IL-1β, TNF-α, and MCP-1." (PMID 36316322, 2022). "Synthetic drugs including mesalazine and azathioprine, and TNF-α blocker such as infliximab have therapeutic effects on UC, but they also have side effects of inducing pancreatitis, cardiomyopathy, systemic reactions, and sweet syndrome." (PMID 35237152, 2022). "IL-1β, TNF-α, IL-6, IL-8, and IL-18 are widely reported pro-inflammatory cytokines that are key indicators for the early prediction and diagnosis of pancreatitis." (PMID 35663952, 2022). "Specific inflammatory cytokines, such as IL-6 and TNF-α, are used to detect inflammation in many cystic conditions and can be used in pancreatitis as well as to distinguish tumors from inflammation in all cystic formations." (PMID 36128446, 2022). "In rats with L-arginine-induced pancreatitis, lycopene treatment reduced tumor necrosis factor-α, myeloperoxidase activity, and inducible nitric oxide synthase gene expression." (PMID 33672594, 2021). "Reportedly, the upregulation of IL-10 in the model of pancreatitis, along with the inhibition of TNF-α, was induced by heme oxygenase-1 (HO1)." (PMID 34122596, 2021). "Excess levels of the inflammatory cytokine TNF plays a prominent role in many inflammatory disease pathologies, including the induction of pancreatitis." (PMID 34049483, 2021). "These networks better illustrate that both, Kras and TNF-α-NFκB pathways were upregulated by pancreatitis to a significantly lesser extent in mice carrying EHMT2 inactivation." (PMID 34249932, 2021).